TNF (tumor necrosis factor)
Diseases named in the same sentence as TNF in open-access papers (continued):
Sharing a sentence is not in itself a finding about the gene and the disease.
type 1 diabetes (continued). "The blockage of TNF-α, eternacept, IL-1β, and anakinra was administered in three patients with type 1 diabetes before and during islet transplantation and all patients achieved insulin independence with normal HbA1c levels by a single infusion from one donor." (PMID 31652814, 2019). "We showed that TNF, probably produced by Tconvs, stimulated Treg proliferation during type 1 diabetes." (PMID 29593717, 2018). "The attenuation of osteoclast formation by the TNF inhibitor has also been shown during the healing process of femoral fracture in type 1 diabetes mice." (PMID 29240821, 2017). "In the latest report on type 1 diabetes, TNF-α was postulated as a key molecule for the elevation of BNP and was demonstrated to be a key player in the development of diabetic complications." (PMID 27478508, 2016). "Cases of juvenile arthritis patients who developed type 1 diabetes have been reported during therapy with a TNF-α antagonist." (PMID 30873466, 2016). "Our study provides another interesting finding that the comparable cEPCs and cECs between groups were concomitant with ~4 fold higher TNF-α concentrations seen in our Type 1 diabetes patients." (PMID 26044827, 2015). "Several studies have shown that DCs, in combination with LPS or TNF-α, inhibit the progression of antiphospholipid syndrome and type I diabetes." (PMID 26107250, 2015). "Within the Type 1 diabetes group, the delta change in cEPCS from rest to the following morning was related to HbA1c (r = -0.65, P = 0.021) and TNF-α (r = -0.766, P = 0.005)." (PMID 26044827, 2015). "TNF-α concentrations were 4-fold higher at all-time points in Type 1 diabetes, when compared with control (P < 0.001)." (PMID 26044827, 2015). "Resting cEPCs and cECs in Type 1 diabetes patients with excellent HbA1c and high physical-fitness are comparable to healthy controls, despite eliciting 4-fold greater TNF-α." (PMID 26044827, 2015). "The Type 1 diabetes group elicited ~4 fold greater TNF-α concentrations at all sample points, when compared to control." (PMID 26044827, 2015). "Among various cytokines involved in promoting and maintaining chronic inflammatory response, TNF-α (tumor necrosis factor-α) and IL-6 are systemically increased in patients with type 1 diabetes." (PMID 24523574, 2014). "In children and adolescents with type 1 diabetes, serum TNF-α, vascular endothelial growth factor (VEGF), AGE concentration, and urinary albumin excretion were all predictive of retinal microvascular disease." (PMID 25258680, 2014). "As with bradykinin-induced Ca2+ mobilization, the difference between the peak Ca2+ concentration between TNF-treated and untreated was much larger in the cells from patients with type 1 diabetes (394±28) compared to the controls (127±20 p = 0.001)." (PMID 24466329, 2014). "Our results also add to the large body of literature that indicates a role for immune activation and proinflammatory cytokines, such as TNF-α, IL-1 and IL-6, in the promotion of beta cell death in type 1 diabetes." (PMID 24264051, 2014). "Animal models of type I diabetes exhibit massive regeneration of the pancreas after elimination of autoreactive T cells with low-dose TNF." (PMID 24391650, 2013). "Inflammatory mediators released from macrophages, such as IL-1β and TNFα, play a key role in early stages of type 1 diabetes." (PMID 24191154, 2013). "When type 1 diabetes was first reversed in end-stage diabetic mice with boosting of TNF, the research showed an unexpected outcome." (PMID 24391650, 2013). "In the case of type 1 diabetes, the rationale for administering TNF is that insulin-autoreactive T cells bear several intracellular signaling defects that make them selectively vulnerable to death upon exposure to TNF." (PMID 22905105, 2012). "We and others have proposed a therapy using TNF-α (or TNFα-inducers such as CFA or BCG) to selectively kill autoreactive T cells in type I diabetes and SS." (PMID 22685592, 2012).
type 1 diabetes (continued). "It stops production of TNF-α, an acute phase inflammatory cytokine, and is found in chronic disease conditions like thyroditis and type I diabetes." (PMID 21702963, 2011). "Proinflammatory cytokines, including IL-1β (interleukin 1β), TNFα (tumor necrosis factor α), and IFNγ (interferon γ), released from immune cells infiltrating the pancreas in Type 1 diabetes, target the β-cells via their respective receptors." (PMID 20182529, 2010). "Both IL-1β and TNF-α contribute to pancreatic β-cell death in type 1 diabetes probably via activation of transcription factor nuclear factor-kappa-B (NF-kappaB)." (PMID 19243577, 2009). "In young patients with type 1 diabetes, cytokine profiles are largely comparable to those of healthy individuals, except for elevated interleukin (IL)-4, tumor necrosis factor alpha (TNF-α), IL-18, vascular endothelial growth factor (VEGF), and angiogenin, alongside decreased IL-10 levels." (PMID 41515940, 2025). "In people with type 1 diabetes, these synergies may reduce or suppress TNF-α and IFN-γ levels.This may be because flavonoids block the tumor necrosis factor-alpha-converting enzyme (TACE), which lowers the amount of TNF-αproduced by NK cells." (PMID 39309571, 2024). "It is conceivable that altered TLR5 signaling may play a role in the increased TNFα levels in patients with type 1 diabetes." (PMID 38482010, 2024). "Therefore, in this study, we aimed to investigate the role of Nuclear factor kappa B (NF-κB) and tumor necrosis factor-alpha (TNF-α) signaling pathway in a type 1 diabetes rat model." (PMID 38821986, 2024). "With the aim to target non‐beta cell–specific inflammatory component, some randomized controlled trials targeting innate immune mediators [such as interleukin (IL)‐6R, tumor necrosis factor alpha [TNFα], and IL‐1] were developed to preserve insulin secretion in stage 3 type 1 diabetes." (PMID 37409229, 2023). "Similarly, higher TNF-α levels have been found in adults with type 1 diabetes and proliferative retinopathy." (PMID 37893230, 2023). "They postulate that early introduction of TNF-α antagonists into treatment regiments of young patients with type 1 diabetes, who appear to have high serum cytokine activity, may prevent the development of diabetic retinopathy." (PMID 37893230, 2023). "Besides, one study reported that higher PA levels (> 250 min/week) were related to a better inflammatory profile (up-regulation of IL-10 and down-regulation of TNF-α) in children with type I diabetes." (PMID 35813370, 2022). "A cluster of positive correlations between the three Th1 cytokines was observed in healthy donors and adults with long-term type 1 diabetes, whereas only TNF-α and IFN-γ MAIT cell production correlated with each other in adults with recent-onset type 1 diabetes." (PMID 34350463, 2021). "In adults with type 1 diabetes, we found that the inflammatory cytokines IL-1α, IL-4, IL-12p70, TNF-α, and the adhesion molecule E-selectin were inversely associated with 24-hour-derived HRV parameters after adjustments for age, sex, disease duration, and smoking." (PMID 32908447, 2020). "Furthermore, as with the STZ-induced model of type 1 diabetes, myocardial tissue of db/db mice showed increased levels of TNF-α, IL-6, and MD2 levels compared with db/m controls." (PMID 32358497, 2020). "The modified cells were then exposed to proinflammatory cytokines mimicking the pathogenic inflammatory beta cell microenvironment of pancreatic islet in type 1 diabetes, i.e. IFNγ/IL1β or IFNγ/IL1β/TNFα and analysed for endogenous XBP1 splicing by qPCR or light emission in cell lysates." (PMID 30532033, 2018). "Interestingly, also vaccines that stimulate endogenous TNF release are currently evaluated as a long-term modulating immuno-intervention in clinical trials in type 1 diabetes and have been investigated in MS (NCT02081326; NCT00607230; NCT00202410)." (PMID 29751683, 2018).
type 1 diabetes (continued). "The results showed that diacerein, via modulation of proinflammatory cytokines (IL-1β and TNF-α), interferes with the onset of type 1 diabetes and may alter the incidence of autoimmune diabetes in treated animals." (PMID 29805981, 2018). "Furthermore, the cytokine secretion profile during the development of type 1 diabetes is typical of a Th1 pattern immune response, with the inflammatory cytokines IL-2, TNF-α, and IFN-γ being secreted in high quantities." (PMID 30254638, 2018). "In type 1 diabetes, pancreatic β-cell failure is mediated by inflammatory cytokines, including interleukin-1β (IL-1β), tumor necrosis factor-α (TNF-α), and interferon-γ (IFN-γ), which may stimulate production of RNS, especially nitric oxide (NO)." (PMID 25949772, 2015). "The enriched ‘Type I Diabetes Mellitus’ gene set includes several genes involved in inflammatory processes, e.g. Human Leucocyte Antigen-molecules, interleukins and TNF, indicating that bleomycin and cisplatin induce an inflammatory response in endothelial cells." (PMID 25590623, 2015). "In conclusion, Type 1 diabetes patients with high cardio-respiratory fitness and excellent glycemic control present normal resting markers of vascular repair (cEPC’s) and injury (cECs), despite being in a persistent inflammatory state (raised TNF-α)." (PMID 26044827, 2015). "Furthermore, our data showed that this blunted response within the Type 1 diabetes group appeared to be predicted by HbA1c and TNF-α concentrations." (PMID 26044827, 2015). "The Idd9.1 region was identified to control type 1 diabetes development through TNF-α." (PMID 24586872, 2014). "Serum TNF-α concentrations over 1.7 pg/mL may point to the presence of diabetic microangiopathy in children and adolescents with type 1 diabetes." (PMID 24688225, 2014). "We found a higher concentration of IFN-γ, TNF-α, and IL-17A in vehicle-treated T cell cultures from donors with type 1 diabetes than in those from control donors, suggesting more cytotoxic T cells, Th1 and Th17 cells, in line with the inflammation associated with type 1 diabetes." (PMID 25279717, 2014). "TNF-α has accelerating role in development of type 1 diabetes." (PMID 24693923, 2014). "We also investigated the regulatory effect of type 1 diabetes on the transcription of genes related to inflammation such tumor necrosis factor-alpha (TNFα), interleukin-6 (IL6), monocyte chemotactic protein 1 (MCP1) and plasminogen activator inhibitor 1 (PAI1)." (PMID 25170835, 2014). "As Il-1β, IFNγ and TNFα are important cytokine effectors of β-cell death in type 1 diabetes, we next sought to determine whether Myt3 is reduced by immune-cell attack in non-obese diabetic (NOD) mice." (PMID 23236509, 2012). "During the course of type 1 diabetes, autoreactive immune cells secrete copious amount of inflammatory cytokines such as IL-1β, TNF-α, and IFN-γ into the islet milieu, which stimulate excessive production of NO in β cells and mediate β-cell destruction by inducing ER stress." (PMID 22454627, 2012). "In addition, the expression of tumor necrosis factor (TNF)-α was significantly upregulated in the retina of a genetic mouse model of type I diabetes." (PMID 21245960, 2011). "In addition, the expression of TNF-α was found unregulated in the retina of a genetic mouse model of type 1 diabetes." (PMID 21245960, 2011). "Thus, with a significant contribution of TNFα produced by the infiltrating immune cells in Type 1 diabetes the resulting greater cytotoxicity is the result of the more pronounced ROS component of TNFα toxicity." (PMID 20182529, 2010). "A meta-analysis of serum TNF-α levels in patients with type 1 diabetes showed that patients with T1D had significantly higher serum TNF-α levels." (PMID 38542165, 2024).
type 1 diabetes (continued). "With the growing focus on type 1 diabetes disease modulation and working towards an ‘insulin free T1D’, our findings strengthen the evidence base for the repurposing of and long-term treatment with anti-TNF-α agents to preserve beta-cell function in new onset T1D." (PMID 39252097, 2024). "However, there have been no studies yet that linked inflammatory biomarkers CRP, IL-6, IL-10, TNF-α, and NF-κB in saliva from adult individuals with type 1 diabetes with and without microvascular complications." (PMID 35788667, 2022). "In support of the value of this approach, we replicated our previous findings in adolescents with Type 1 diabetes, observing elevated levels of all five inflammatory markers chosen for our risk score, but no observable differences in IL-6 or TNF-α levels (P = 0.851 and 0.224; data not shown)." (PMID 30863865, 2019). "Therefore, we aimed to analyze the levels of cytokines, IL-6, TNF-α, VEGF, and IL-10, in serum of girls with type 1 diabetes and find out whether estrogen receptor α polymorphism has relevance for their production." (PMID 24523574, 2014). "One of the main reasons for the development of type I diabetes is that cytokines such as IFN-γ, TNF-α, and IL-1β produced by immune cells break down the islet beta cells." (PMID 36386181, 2022). "Astilbin decreased TNF-α and IFN-γ production and increased CCR9 expression of CD4+ T cells, and played a protective role in the onset of type 1 diabetes." (PMID 35652039, 2022). "In model mice with STZ-induced type 1 diabetes, in which a decrease in skin AQP3 was observed, both the blood TNF-α concentration and cutaneous TNF-α expression were increased." (PMID 33494453, 2021). "Macrophages not only induce β cell damage or death by releasing TNF-α, IL-1β, and ROS but also promote efficient differentiation of diabetogenic CD8+CTLs leading to type 1 diabetes onset." (PMID 33690220, 2021). "During the initial stage of type 1 diabetes, β-cells are exposed to the proinflammatory cytokines, such as IL-1β, IFN-γ, and TNF-α, released by the infiltrated immune cells." (PMID 34054343, 2021). "The mechanism is potentially related to reduction in inflammatory responses as plasma levels of TNF-α and GRO-α were decreased, while the cell survival marker HGF was increased in human islets exposed to a type 1 diabetes-like milieu in vitro and in vivo." (PMID 32350565, 2020). "One of the important mechanisms of beta cell damage during type 1 diabetes is increased expression of proinflammatory cytokines such as IL-1β, IFN-γ and TNF-α and cytokine induced beta cells were commonly used as in vitro model of type 1 diabetes." (PMID 30974824, 2019). "Proinflammatory cytokines (such as IFN-γ, TNF-α, and interleukin 1β (IL-1β)) promote beta-cell destruction and exacerbate autoimmunity, which may ultimately lead to type 1 diabetes (T1D)." (PMID 31443415, 2019). "A study also showed that RA decreased plasma triglyceride and cholesterol levels and declined cardiac and renal levels of tumor necrosis factor-α (TNF-α) and monocyte chemoattractant protein-1 in streptozotocin-induced type 1 diabetes mice." (PMID 31887996, 2019). "Indeed, in murine models of type 1 diabetes or lupus nephritis, TNF may have a protective effect." (PMID 29593717, 2018). "For most of the genes analyzed, transcripts levels were markedly decreased in response to type 1 diabetes except PPARγ and TNFα in eWAT, MCP1 in scWAT and PPARγ, IL6 and TNFα in rWAT." (PMID 25170835, 2014). "In the course of Type 1 diabetes pro-inflammatory cytokines (e.g., IL-1β, IFN-γ and TNF-α) produced by islet-infiltrating immune cells modify expression of key gene networks in β-cells, leading to local inflammation and β-cell apoptosis." (PMID 22347430, 2012). "The levels of anti-inflammatory (IL-35, IL-10, IL-4) and proinflammatory (TNF-α, IL-12, IL-18) cytokines were statistically comparable between the type 1 diabetes patients with Hashimoto’s disease and those without." (PMID 39273664, 2024).
type 1 diabetes (continued). "In fact, TNF-α has been detected in the serum of children and young adults with type 1 diabetes and non-proliferative diabetic retinopathy." (PMID 38542165, 2024). "Type 1 diabetes is an autoimmune disorder, in which auto-reactive T-cells (CD4 and CD8) produce pro-inflammatory cytokines such as TNF and IFNγ, which are able to mediate pancreatic beta cell death and activate macrophages, leading to further cytokine production and increased beta cell destruction." (PMID 37762318, 2023). "TNF-α has been found in the serum of children and young adults with type 1 diabetes and non-proliferative diabetic retinopathy." (PMID 37893230, 2023). "Moreover, the study revealed a hyperglycemic environment promotes the activation of NF-κB signaling pathway, upregulates the expression of TNF-α, MCP-1, and IL-1β, thereby contributing to the renal damage in type 1 diabetic mice." (PMID 34253875, 2022). "Since we noted that astilbin could reduce IFN-γ and TNF-α in CD4+T cells, we then analyzed whether astilbin could repress the onset of type 1 diabetes in NOD mice by regulating CD4+T cells." (PMID 35652039, 2022). "In addition, the topical application of propolis on diabetic wounds has reduced/declined IL-1β, IL-6, TNF-α, and MMP9 levels in STZ-induced type I diabetic mice." (PMID 35047540, 2021). "In adults with long-term type 1 diabetes, MAIT cells displayed an activated and exhausted phenotype characterised by high CD25 and programmed cell death 1 (PD1) expression and a decreased production of proinflammatory cytokines, IL-2, IFN-γ and TNF-α." (PMID 34350463, 2021). "Interestingly, MAIT cell IL-17 production positively correlated with MAIT cell TNF-α production in healthy donors and also with other Th1 cytokine production (IFN-γ and IL-2) in individuals with long-term type 1 diabetes." (PMID 34350463, 2021). "This study aimed to examine cEPCs, cECs and TNF-α at rest, and in response to acute submaximal exercise, in physically fit males with and without Type 1 diabetes." (PMID 26044827, 2015). "For example, the downregulation of type 1 diabetes (T1D) in the non-obese diabetic (NOD) mouse by CFA immunisation has been shown to involve TNFα production and granzyme B/perforin-secreting Treg." (PMID 18380898, 2008). "Indeed, there is evidence that TNF-α is detectable in the serum of children and young adults with type 1 diabetes who also have nonproliferative diabetic retinopathy." (PMID 39273664, 2024). "The same authors have shown that the TNF-α level may be an independent predictor for the development of non-proliferative diabetic retinopathy in children with type 1 diabetes." (PMID 37893230, 2023). "However, our results show that reduced capillary density and high levels of TNF-α and VEGF can precede the onset of microangiopathic complications in type 1 diabetes and may help predict abnormal microvascular reactivity." (PMID 37893230, 2023). "In animal models of type 1 diabetes, SOCS1 has been suggested to be involved in the regulation of inflammatory cytokines such as IFN-γ and tumor necrosis factor alpha, which are responsible for the destruction of pancreatic β cells, and SOCS1 may protect β cells from cytokine-mediated destruction." (PMID 37110462, 2023). "In 543 patients divided into two groups based on the presence or absence of any complication of type 1 diabetes, circulating levels of C-reactive protein, interleukin-6, and tumor necrosis factor-α were increased in individuals with complications compared with those without." (PMID 29910771, 2018). "In the early stage of type 1 diabetes, the autoreactive immune cells such as macrophages and T lymphocytes infiltrate into the pancreatic islets along with the secretion of inflammatory cytokines such as IL-1β, IFN-γ, and TNF-α, which then induce ER stress to mediate β-cell destruction." (PMID 22454627, 2012).
type 1 diabetes (continued). "Obese children with new onset type 1 diabetes are more likely to have higher pro-inflammatory markers (leptin, visfatin, chemerin, TNF-α, CRP) and lower anti-inflammatory markers (adiponectin, omentin) compared to non-obese peers with type 1 diabetes." (PMID 33828529, 2021).